CD4 (CD4 molecule)
Diseases named in the same sentence as CD4 in open-access papers (continued):
Sharing a sentence is not in itself a finding about the gene and the disease.
tumor (continued). "In contrast, the activity of tumor-infiltrating CD4+ and CD8+ T cells was significantly enhanced by cisplatin, as evaluated by their ability to secrete cytokines, e.g., INF-γ and TNF-α." (PMID 39343834, 2024). "The tumor tissues were immunohistochemically stained with CD4-, CD8-, CD11c-, CD86- and GFP-specific Ab to assess immune cells infiltration." (PMID 38835775, 2024). "Breast tumors recruit CD1a+ immature dendritic cells by releasing CCL20 and then instruct those immature dendritic cells to prime IL-13 secreting CD4+ T cells that facilitate tumor development." (PMID 38786066, 2024). "Generally, the CD8+ cytotoxic T cells (CTL) and the CD4+ helper T1 (Th1) cells eliminate tumor cells via an interferon-γ (IFN-γ) and cytotoxin-mediated mechanism." (PMID 38994941, 2024). "On the other hand, N2 neutrophils contribute to tumor progression within the TME by recruiting immunosuppressive CD4+ T cells and by upregulating CCL2, which enhances angiogenesis." (PMID 39057061, 2024). "A single injection revealed a large increase in CD4+/8+ T cells in mice, inhibition of tumor growth, and prolongation of survival." (PMID 38611742, 2024). "Klug and co-workers showed that LDRT shifts pro-tumor M2-macrophages towards the anti-tumor M1-phenotype, increases the infiltration of CD4+ T cells and Natural Killer cells, and downregulates the expression of the inhibitory cytokine TGF-β." (PMID 39044839, 2024). "During related mechanistic studies, it was found that there were more CD155 tumor cells and CD4+ CD25+ Tregs, with increased TIGIT levels following aspirin treatment." (PMID 39227959, 2024). "Serial dilutions of engineered fluorescent tumor cells were mixed with either CD4+ or CD34+ primary cells, and their growth was followed." (PMID 39416278, 2024). "Often overlooked, there is accumulating evidence suggesting that CD4+ T cells are at least as critical as cytotoxic CD8+ T cells for efficient tumor clearance." (PMID 38306431, 2024). "The proportion of ADR+ cells in CD4+Foxp3+ Tregs in the spleen, liver, and tumor tissues was analyzed by FACS." (PMID 39247806, 2024). "The quantity of CD4+ T lymphocytes and the level of the tumor marker CEA were shown to be negatively correlated." (PMID 38259671, 2024). "A higher CD4/CD8 ratio in the tumor microenvironment was also noted in patients whose tumors had antitumor activity to afatinib/pembrolizumab, but this was not statistically significant (p = 0.4) with a small sample size." (PMID 39318388, 2024). "HP-NAP activates neutrophils and monocytes, promoting IL-12 and IL-23 production, which polarizes a CD4 + T cell response into an anti-tumor Th1 response characterized by increased IFN-γ and TNF-α." (PMID 38641815, 2024). "We used baseline measurements of patient avatars, identifying some commonalities such as CD4+ T cell proximity to tumor cells and to B cells." (PMID 38968363, 2024). "A heatmap of immune cell infiltration confirmed that increased TIMELESS expression was associated with CD4+ T and Th2 cell infiltration in TCGA LUAD tumor tissues." (PMID 38261568, 2024). "This vaccine was able to induce antigen-specific CD4 T-cell responses and a sufficiently strong humoral response to delay tumor growth in mice as a monotherapy, but also synergistically with ICI." (PMID 38793784, 2024). "It is an effector cytokine involved in the polarization of CD4+ T cells towards a Th1 response that is crucial for the activation of both cytotoxic T and NK cells and tumor clearance." (PMID 39411143, 2024). "An OV-mOX40L treatment also increases the infiltration of CD4+ T cells, decreases the tumor-infiltrating CD8+ T cell exhaustion, reduces FOXP3+ regulatory CD4+ T cells, and reprograms macrophages and neutrophils to a pro-inflammatory state." (PMID 39845957, 2024).
tumor (continued). "At D7 and D10, we demonstrate a tumor growth control mediated by CD4+ (p< 0.01 and p= 0.055, respectively for D7 and D10) and total GMTC (p< 0.01 and p< 0.05, respectively for D7 and D10), but not by CD8+ GMTC group, compared to total UTC control group." (PMID 38545119, 2024). "Both deeper understanding and the rational targeting of autologous CD4+ T cells are required to maintain a durable and powerful anti-tumour response when using CD4+ T cell immunotherapy for MPE if clinical benefits are to be achieved." (PMID 38475858, 2024). "Th1 subtype CD4+ T cells contribute to anti-tumor activity by assisting cytotoxic CD8+ T cells and B cells and directly killing cancer cells through interferon and tumor necrosis factor-alpha production." (PMID 39926600, 2024). "The activation of both tumor‐specific CD4+ and CD8+ T cells enhances the anti‐tumor effects of the body." (PMID 39463159, 2024). "This is different for various types of tumors, indicating that different phenotypes of CD4+ T lymphocytes play roles in shaping the tumor microenvironment (TME)." (PMID 38690280, 2024). "These CD4 + FoxP3 + Eomes + T cells also express Granzyme B, a marker of cytotoxicity, and are able to clear the tumor in a CD8 + T cell-deprived mouse model." (PMID 38355394, 2024). "Recent studies have also indicated that immune checkpoint blockade can mediate the normalization of tumor vasculature via CD4+ T cells in an IFN-γ-dependent manner." (PMID 38398223, 2024). "CD4+T cells play a great role in tumor immunity, and can bind to DC-Exo generated by tumor cells to induce tumor immunity." (PMID 38994350, 2024). "The result showed that C3 has the highest level of MHC-II interaction with CD4+ T cells, suggesting that the C3 tumor cells are particularly important for robust antitumor responses." (PMID 39664386, 2024). "More work is being done to understand the divergent effects of Th1 and Th2 CD4+ T cells in the tumor microenvironment." (PMID 38786066, 2024). "It was suggested that fibroblasts suppressed CD8+ T cells and CD4+ T cells and fostered tumor immune suppression." (PMID 39582060, 2024). "To further examine the spatial relationship between CD8+ T cells, CD4+ T cells, and tumor cells, we introduced the spatial score to describe which cell type CD8+ T cells were more likely to interact." (PMID 38611111, 2024). "We found that RocA promoted the infiltration and differentiation of CD4+ TILs and coordinated with anti-PD-1 antibody to overcome checkpoint resistance in multiple tumor models." (PMID 38833034, 2024). "Based on previous studies and the observation of local TCR clone expansion, the expression of ITGAE/ENTPD1 was considered to serve as a general marker for tumor‐reactiveness also for these CD4+/CD8+ T cells." (PMID 38582099, 2024). "Mice lacking CD8+ T cells were unable to control PD-L2 KO tumors after chemotherapy, while control animals or mice treated with anti-CD4-depleting antibodies had robust suppression of tumor growth." (PMID 38267628, 2024). "We first examined CD4+ T cells and CD8+ T cells, two types of lymphocytes closely associated with tumor progression, in the bronchoalveolar lavage fluid (BALF) by flow cytometric analysis." (PMID 38195889, 2024). "We found that CD4+ T cells were associated with CEA expression, indicating that older patients with lower tumor differentiation tended to have higher CEA expression and worse overall survival rates." (PMID 38259671, 2024). "Follicular helper T cells are a subgroup of CD4+ T cells, which induced anti-tumor immunity by facilitating the differentiation and maturation of tumor-killing cells." (PMID 39074262, 2024). "The depletion of CD4+ T cells prevented anti-tumor effects of the anti-CTLA-4 Ab, whereas depletion of CD8+ T cells had little effect in the Hepa1-6 model." (PMID 39106430, 2024).
tumor (continued). "They maintain a balance with Treg cells, with which they share common precursor cells (naïve CD4+ T cells) and require a common tumor growth factor-β signal for initial differentiation." (PMID 38369554, 2024). "YTHDF1 expression was linked with tumor purity (r = 0.152, p = 1.44 × 10−6), B cells (r = 0.07, p = 2.96 × 10−2), CD8+ T cells (r = 0.175, p = 3.53 × 10−8), CD4+ T cells (r = 0.089, p = 2.96 × 10−2)." (PMID 38339157, 2024). "Eventually there was significant correlation between PD-L1 IC and the number of tumour-infiltrating CD4+ T cells (r = 0.279, p = 0.018), as well as Foxp3+CD4+ T cells (r = 0.251, p = 0.034)." (PMID 38541208, 2024). "Overall, CD8+ T cells, CD4+ T cells, NK cells, and B cells reveal anti-tumor properties, while Tregs, similar to fibroblasts, M2 macrophages, or MDSCs, promote HCC progression." (PMID 39408564, 2024). "The distance between CD8+Tregs and tumor cells or CD4+T cells in IM and TC decreased with the advancing TNM staging, while the distance between CD8+Tregs and CD8+T cells in IM and TC increased (all P < 0.05)." (PMID 39093404, 2024). "In summary, the impact of tumor-infiltrating CD4+ T lymphocytes on HCC progression is intricate and contingent upon the context." (PMID 38426090, 2024). "These vaccines induce an antigen-specific CD8+ and CD4+ T-cell response to enhance anti-tumor activity based on a patient’s individual tumor." (PMID 39057120, 2024). "The immune tumor environment comprises T cells (CD4+, CD8+, Tregs), natural killer cells (NK cells), macrophages (TAMs—tumor-associated macrophages), dendritic cells, and MDSCs (myeloid-derived suppressor cells)." (PMID 39195233, 2024). "MIP1α, CD137 (4-1BB), and Granzyme B were upregulated in tumor-infiltrating CD4+ T cells, indicating their activation and effector function." (PMID 39044839, 2024). "We observed that the anti-tumor effect of zebularine was abolished in the presence of anti-CD8 or anti-CD4 antibodies in B16F10 tumor-bearing mice or MC38 tumor-bearing mice." (PMID 38755254, 2024). "The CD4+ T cells play dual opposing roles in tumor progression, displaying anti- and pro-tumorigenic properties." (PMID 38673829, 2024). "DCs then process and present tumor antigens derived from the vaccinating cells to the effector T cells (CD4 and CD8) via the formation of antigen–MHC complexes on the DCs, and T cells bind to this complex with their T cell receptors (TCRs)." (PMID 38672519, 2024). "A similar reduction of GZMB/CCL5-expressing CD4+ TILs was observed when a comparison was made between 1956 tumour-bearing WT mice and mice with a targeted disruption of the Lilrb4 gene." (PMID 39048822, 2024). "Inversely, a lower proportion of Th2 (IL-4+ CD4+ T cells) cells was detected in both tumor types compared to NS (BCCs, median: 8.3%, range: 2.4–15.6; SCCs, median: 7.3%, range: 3.7–13.1; NS, median: 19.2%, range: 9.4–30.9)." (PMID 38891095, 2024). "The biological activity of VTCN1 is associated with inflammatory CD4+ T-cell responses and VTCN1- expressing tumor-associated macrophages and FoxP3+ regulatory T cells (T regs) within the tumor microenvironment." (PMID 39116105, 2024). "CD8+T cells, CD4+T helper cells, and Tregs were closest located to each other (CD8+T cells to CD4+T helper cells 23 μm and to Tregs 33 μm) and to macrophages (30 μm), while tumor cells were situated further away (55 μm), and B cells even more so (67 μm)." (PMID 39053947, 2024). "Tumor-antigen-specific CD4+ T cells exhibit early transient expansion but rapidly develop anergy in tumor-bearing hosts." (PMID 39438986, 2024). "Pinz and colleagues demonstrated that modified CD8+ T cells expressing CD4 CAR induced robust anti-tumor effects in vivo, and CAMPATH was used as a natural safety switch to prevent unwanted toxicities." (PMID 39462383, 2024).
tumor (continued). "There were more tumor-infiltrating CD4- and CD8-positive cells in the ICG-Lipo-PTX group on the PDT and non-PDT sides than in the control group, although the difference was not significant." (PMID 38515576, 2024). "Within the tumor microenvironment, IL-16 can attract CD4+ T cells and other immune cells to the tumor site, promoting both pro-tumorigenic and antitumorigenic effects." (PMID 39408600, 2024). "The results conclusively demonstrate a substantial influx of lymphoid anti‐tumor immune cells, such as CD4, CD8 T cells, and NK cells upon Gsdmc inhibition, accompanied by a reduction in M2‐type TAMs." (PMID 39297408, 2024). "This was indicative of the inability of these mice to develop robust immune memory to B16F10 tumor cells, likely resulting from the depletion of CD4+ effector T cells which are necessary for proper formation of CD8+ memory T cells." (PMID 38429261, 2024). "The importance of T cells during tumor-targeted therapy was investigated by depleting CD4+ or CD8+ T cells in tumor-bearing mice." (PMID 38631706, 2024). "In the study, they also demonstrated how the increased expression of MHC Class II is a strong stimulus that promotes the accumulation of tumor-specific CD4+ T cells in the tumor microenvironment." (PMID 39796650, 2024). "The presence of infiltrated cytotoxic CD4+ T cells in tumor tissue decreases as HCC progresses, with peaks observed only during the early stages of the disease." (PMID 38426090, 2024). "Accordingly, the DPT percentage was decreased both in the spleen and tumor in mice with anti‐CD4 treatment in comparison with IgG treatment." (PMID 39225354, 2024). "We chose antibody clones that showed appropriate regional (e.g., splenic white pulp) and subcellular localization (e.g., cell membrane for CD3ε, CD4 and CD8α and nucleus for FoxP3) in spleen and tumor tissue." (PMID 38605049, 2024). "An analysis of the tumour-immune phenotype revealed a significant association between PD-L1 expression and IL17+CD4+ and Foxp3+CD4+ immune phenotypes." (PMID 39409156, 2024). "Afterward, these immune cells with suppressive properties can then prompt the transformation of initial CD4+ T cells into regulatory T cells (Tregs) specific to tumor antigens, ultimately hindering the activity of CD8+ T cells that target the tumor." (PMID 38420194, 2024). "In comparison to Tregs, proinflammatory CD4+ Th17 cells appear to exhibit high aerobic glycolysis, which is a prerequisite for IL‐17 and IL‐22 production, thereby enhancing self‐renewal and tumour cell proliferation, respectively." (PMID 38468489, 2024). "cDC2 cells mainly stimulate the proliferation of CD4+ T cells, thereby participating in the anti-tumour immune response." (PMID 38475858, 2024). "Further mechanistic analysis indicated that treatment with mIL12 led to a substantial increase in tumor-infiltrating CD4+ T, CD8+ T, cDC1, and CD103+ cDC1 cells." (PMID 39584994, 2024). "In this study, we focused on the mechanism that BCL6 inhibits the tumor infiltrating CD4+T cells through ESM1, however, there are other mechanisms through which BCL6 promotes HCC progression." (PMID 38956432, 2024). "CD4+ T cells were previously demonstrated to promote anti-tumor immunity and enhance immunotherapy through multiple pathways." (PMID 38419527, 2024). "Similar to the tumor microenvironment, a significant decrease in CD4+ PD1+ T cells in the spleen was observed as well as exhausted CD8+ T cells and T regulatory cells when MPO was deficient." (PMID 38367056, 2024). "Previously, we also demonstrated the CD4+ Th1-dominant immunity at the late stage after cryo-thermal therapy coordinates both innate and adaptive immunity to induce long-lasting tumor cytotoxicity and improve the tumor-free survival of mice." (PMID 38827732, 2024). "The flow cytometry quantified that the percentage of CD4+ T cells in tumor tissue of Group 4 mice was 3.3‐fold of control group." (PMID 39021327, 2024).
tumor (continued). "A low level of tumor cell pyroptosis caused by GSDMA3 induces effective antitumor immunity, including increased CD3+, CD4+, and CD8+ cell populations." (PMID 38711020, 2024). "In melanoma-bearing mouse models, butyrate supplementation with anti-PD-1 therapy significantly reduced tumor volume and increased the percentage of IFN-γ+ and tumor necrosis factor (TNF)-α+ cells among tumor infiltrating CD4+ and CD8+ T cells." (PMID 39840031, 2024). "CD4+IL-4+ T lymphocytes act as indirect promoters of invasion and metastasis by regulating the increase in macrophages in the tumour microenvironment." (PMID 38662248, 2024). "Increased CD-3, CD-4, and CD-68 staining occurred in the tumor transplant area around the regions of tumor necrosis in immune-reconstituted TPV/eGFP subjects when compared to immunocompromised TPV/eGFP-treated mice." (PMID 39200298, 2024). "For both TI-Treg gene signatures, we computed a score for each intra-tumor CD4+ T cell of the atlas." (PMID 39729479, 2024). "All MSI-H CRCs were subjected to digital pathology-based quantification of CD3 + /CD8 + /CD4 + /FoxP3 + /CD68 + /CD204 + /CD177 + tumor-infiltrating immune cells using whole-slide immunohistochemistry." (PMID 39235590, 2024). "Single-cell TCR sequencing identified a clonal relationship between CD4+ T cells in the gut and those in the tumor microenvironment, suggesting a potential migratory pathway." (PMID 39185202, 2024). "AG has also been suggested to alter the tumor microenvironment by increasing the infiltration of CD4+ T cells or directly recruiting the neutrophils from peripheral blood to destroy tumors." (PMID 38088444, 2024). "By activating the immune system, CD4+ T cells can enhance the recognition and elimination of tumor cells, thereby inhibiting tumor growth and spread." (PMID 38953025, 2024). "T cells (CD8+ and CD4+) are an important component of the adaptive immune system and play a key role in eliminating tumour cells via various cytotoxic activities." (PMID 38352889, 2024). "Tumor-infiltrating CD4+ and CD8+ T cells usually express the B cell-recruiting C-X-C motif chemokine ligand 13 (CXCL13), possibly to request B cells help." (PMID 38629061, 2024). "The tumor-infiltrating CD4+T cells were isolated by magnetic beads, and the purity was confirmed to be >95%." (PMID 38891044, 2024). "Antigen-presenting DCs then activate tumor-infiltrating T and B lymphocytes or stimulate CD4+ Tfh cells within TLS, initiating the cascade of B-cell proliferation and differentiation." (PMID 39026670, 2024). "The balance of pro-tumor and anti-tumor functions of CD4 + T cells largely determines the immunogenicity of the tumor microenvironment." (PMID 38671491, 2024). "For both primary and secondary tumorsin Hepa1-6 and 4T1 tumor models, all mice treated with AMPNs and anti-PD-1alone demonstrated an increasing fraction of CD4+ and CD8+ T cells in TIME, with the largest increase in the AMPNs +anti-PD-1 group." (PMID 39051165, 2024). "Adoptive transfer of HDVax-induced LILRB4+SEMA4a− or LILRB4+SEMA4a+ mItgb1-specific CD4+ T cells comparably ablated T3 tumour rejection in the Rag2−/− ACT assay." (PMID 39048822, 2024). "Peritumoral administration of HP-NAP resulted in a reduction of tumorigenesis, promotion of tumor necrosis, and augmentation of CD4 + and CD8 + cell populations secreting IFN-γ within both tumor sites and associated lymph nodes." (PMID 38641815, 2024). "The 13F3-treated mice showed a markedly slower tumor growth, whereas the anti-leukemic effect of 13F3 in WT B6 mice was inhibited by removing T cells with CD4 and CD8 monoclonal antibodies." (PMID 39742253, 2024). "In response, a vaccine adjuvant, DC hyper-activators, was developed to restore DCs’ migration, enhance anti-tumor CD4+ T cell responses, and bolster tumor immunity in aged mice." (PMID 39599617, 2024).